IL6 (interleukin 6)
Diseases named in the same sentence as IL6 in open-access papers (continued):
Sharing a sentence is not in itself a finding about the gene and the disease.
Fever (continued). "Hyperthermia and fever are initiated following exposure to exogenous (bacteria, toxin) or endogenous pyrogens (pro-inflammatory cytokines (IL-1β, IL-6 and tumor necrosis factor-α (TNF-α))." (PMID 22971439, 2012). "Similarly, Atlantic salmon (Salmo salar) infected with infectious pancreatic necrosis virus (IPNV) exhibited behavioral fever, increasing their preferred temperature and upregulating pro-inflammatory cytokines (IL-1β, IL-6, TNF-α)." (PMID 40508975, 2025). "It is speculation to conclude that this patient benefited from IL-6 antagonism in addition to the likely beneficial reduction of pyrexia." (PMID 40299000, 2025). "This marked production of potent endogenous pyrogens such as IL-1β, IL-6 and TNF-α, can interact directly with the anterior hypothalamus, through a hierarchy of neural structures, and raise the temperature setpoint, causing fever." (PMID 39928662, 2025). "Furthermore, women with maternal pyrexia showed a 1.5 fold increased level of Interleukin-6 during labour." (PMID 38702618, 2024). "Fever symptoms appear when IL-6 is excessively produced in an inflammatory response to LPS." (PMID 36768389, 2023). "Accordingly, children with fever have been found to have significantly elevated levels of serum IL-6 compared with control children, and those with fever and more episodes of diarrhea had significantly higher levels of TNF-α than those without fever and with fewer episodes of diarrhea." (PMID 36976000, 2023). "In the case of pyrogenic pyrexia, the generation of fever involves several mechanisms, most commonly exogenous pyrogens such as microbes or endogenous pyrogens such as interleukin 1 (IL-1) or interleukin 6 (IL-6)." (PMID 36296631, 2022). "In our experiments, it was confirmed that SHL could reduce the pro-inflammatory cytokines TNF-α, IL-6, and IL-1β in LPS-induced fever rats in order to play an antipyretic and anti-inflammatory effect." (PMID 35837285, 2022). "Transient increases in levels of C-reactive protein, ferritin (and decrease in iron), IL-6, and/or IL-8 with pyrexia and vomiting during dose escalation in three patients were characterized by investigators as acute phase reactions and led to dose adjustments at the next infusion." (PMID 33875845, 2021). "Fever is a strongly linked environmental trigger of human HSV reactivation either through a direct effect on latently infected neurons and/or the secretion of pyrogenic cytokines including IL-6." (PMID 34667693, 2021). "Functionally, IL-6 has been reported to promote inflammation and pyrexia." (PMID 33195706, 2020). "Furthermore, it is understood that IL-6 acts in concert with IL-1β as an endogenous pyrogen during LPS-induced fever." (PMID 30674283, 2019). "In conclusion, the fever which we observed in calves after administering Cp into the lungs was caused by a locally generated inflammatory cascade rather than circulating IL-6." (PMID 29281663, 2017). "IL-6 plays an important role as an endogenous mediator in LPS-induced fever." (PMID 26829940, 2016). "All GMMA with lipid A modification showed a marked decrease of cytokine release compared with GMMA with WT lipid A. IL-6 release was chosen for detailed comparison of the relative ability of GMMA to elicit cytokine release due to its role in fever pathogenesis." (PMID 25023285, 2014). "Like IL-1β, IL-6 induces the production of acute phase proteins, pyrexia and sickness behaviour." (PMID 24134207, 2013). "A decade and a half ago, detailed analysis of cytokine release in the early phase of JHR showed that TNF concentration increases within 30 min following penicillin administration and that this increase preceded pyrexia and the rises in plasma IL-6 and IL-8 concentrations." (PMID 24198733, 2013). "Moreover, it has been reported that IL-6 is a pro-inflammatory cytokine, regarded as endogenous mediator of LPS-induced fever." (PMID 20205748, 2010).
Fever (continued). "Interestingly, it has also been reported that TNFα-induced pyrexia in mice was largely mediated by IL-6 production." (PMID 20463923, 2010). "Thus, we speculate that the favorable effect of this spore-based probiotic on fever was due to its effect on proinflammatory markers, especially IL-6." (PMID 36771194, 2023). "Therefore, attenuating IL-6 expression in cardiomyocytes may be an essential strategy to minimize the systemic inflammatory response often referred to as rebound pyrexia in hypothermia-treated cardiac arrest patients." (PMID 31871429, 2019). "MP, a common exogenous pyrogen, stimulates the production of numerous inflammatory factors in the body, including IL-6, IL-10, and IFN-γ, potentially leading to persistent fever or even hyperpyrexia." (PMID 40656192, 2025). "The fever group had significantly increased serum levels of TNF-α, IL-1β, IL-6 and PTGS2 (p < 0.05, p < 0.01) compared to the control group." (PMID 40430430, 2025). "Fever was induced using turpentine, an exogenous pyrogen that stimulates endogenous pyrogens such as TNF-α, interferon-gamma (IFN-γ), IL-1β, and IL-6 to initiate the synthesis of PGE2." (PMID 41245555, 2025). "Compared with the NG, the mRNA expressions of TNF-α, IL-6, IL-1β, NF-κB, TRPV4, and HSP70 in the MG were significantly upregulated (P < 0.01), indicating that the expression of mRNA was enhanced under fever conditions." (PMID 40356990, 2025). "The interleukin cytokines IL6, IL27, and IL17B, were upregulated in the medium and high dose groups resulting in hemorrhagic fever by cytokine storm." (PMID 35854219, 2022). "Hyperthermia increases the amount of calreticulin in TME and consequently induces ICD.Hyperthermia increases the expression of IL‐6, IFN‐γ, and TNF‐α." (PMID 35908281, 2022). "In order to explore the antipyretic effect of HLJDD on LPS-induced fever in rats, we detected the expression levels of TNF-α and IL-6 in the serum and PGE2 and cAMP in the hypothalamus tissue of fever rats." (PMID 35003291, 2021). "The activities of IL1β and IL6 are similar to TNF-α, including the induction of pyrexia and the production of acute phase proteins." (PMID 31918707, 2020). "Fever has been correlated with PMN infiltration into the lung, as well as with IFN-α, TNF-α, IL-1, and IL-6 production in response to SIV infection." (PMID 23074662, 2011). "Kidney tissues from fever seahorses exhibited significantly higher mRNA expression levels of tnf-α, il-6, ifn-g, and il-10 compared to the no-fever group (p < 0.05)." (PMID 40508975, 2025). "We analyzed the correlations among CRS, fever, PCT, IL-6, and CRP." (PMID 38956649, 2024). "PPGL combined with persistent elevated inflammatory markers, either in the presence or absence of pyrexia, raised suspicion of IL-6 overproduction in these three patients." (PMID 33715142, 2021). "Remarkably, during behavioural fever at 48 hpi, Il1β, Il6, and Tnfα1 protein levels were higher than those in the no-fever individuals." (PMID 34445566, 2021). "IL6, IL1, TNF-α, TGF-β and IFN-γ, endogenous pyrogens, leading to high pyrexia." (PMID 33173434, 2020). "One of our patients with a non-functional malignant PGL presented with pyrexia resistant to any treatment due to IL-6 ectopic secretion." (PMID 31137729, 2019). "Further warming to pyrexia resulted in the greatest increases in IL-6 transcriptions in both cooled and noncooled OGD/R groups relative to both normoxia control and OGD/R groups maintained at or rewarmed to 37°C (41 and 53 h)." (PMID 31871429, 2019). "The levels of IL-6 in pyrexia rats treated with GF (47.51 ng/l), GFP (61.7 ng/l), and GFC (47.5 ng/l) were decreased versus those observed in the PM group (67.62 ng/l), while those of IL-6 in the GF and GFC groups were markedly decreased (∗∗P < 0.01)." (PMID 31143120, 2019). "Controls inoculated with either inactivated Cp or BGM cells also expressed increased bioactive IL-6, but no fever developed." (PMID 29281663, 2017).
Fever (continued). "This syndrome is characterized by the presence of pyrexia, tachycardia, hypotension, tachypnea, myalgia, transient confusion, delirium, aphasia, and seizures, among other symptoms mimicking sHLH in our case, and it is secondary to high amounts of TNF-a and IL-6 being released." (PMID 36195892, 2022). "Notably, AE incidence and severity (rash, hypotension, pruritus, and pyrexia) declined on continued dosing, no anti-IL-6 therapy was required, and no treatment-related deaths occurred, underscoring a predictable, front-loaded but controllable safety profile for tebentafusp." (PMID 41598579, 2026). "Therefore, the inflammation‐suppressive action of the bioactive components of Fevogrit could well be the primary mode of action of Fevogrit against LPS‐induced fever, as shown by the reduced levels and gene expression of TNF‐α, IL‐1β and IL‐6 in serum and hypothalamus, respectively." (PMID 39021318, 2025). "We found that LPS treatment could significantly increase the rectal temperature and dorsal interscapular surface temperature (contribute to fever) of mice, and the mRNA levels of TNFα, IL-6, Ucp1, and Pgc1α in the BAT, but did not affect the expression of Cpt1α and Cidea." (PMID 36430282, 2022). "For example, in children following rotavirus gastroenteritis, significantly increased serum levels of IL-6 and TNF have been reported in fever patients more than in those without." (PMID 37403122, 2023). "Combination of persistent elevated inflammatory markers, either in the presence or absence of pyrexia, and the presence of PPGL, raised suspicion of IL-6 overproduction in our patients." (PMID 33715142, 2021). "Although Histoplasma infection stimulated the production of pyrogenic cytokines (i.e., IL-1β, IL-6, and TNF-α), pyrexia is not induced in mice." (PMID 29295913, 2018). "Even though previous cooling attenuated this increase in IL-6 after 12-hour exposure to pyrexia (41 h) in the cooled OGD/R group compared to the noncooled OGD/R group, this protective effect was no longer observed after 24-hour exposure to pyrexia (53 h)." (PMID 31871429, 2019).
glaucoma (103 papers, 2010 to 2026). Increased pressure in the eyeball due to obstruction of the outflow of aqueous humor. "Alterations in the levels of CRP and interleukin-6 (IL-6) in glaucoma, along with their associations with the disease, warrant further investigation." (PMID 40440644, 2025). "UPF consumption has also been linked to an increase in interleukin-6 (IL-6) levels, which has been linked to the survival and degeneration of retinal ganglion cells and the development of glaucoma." (PMID 38613086, 2024). "IL-6 has been implicated in numerous fibrotic eye diseases, including glaucoma filtration surgery (GFS), posterior capsular opacification (PCO) and proliferative vitreoretinopathy (PVR)." (PMID 36147459, 2022). "Single‐nucleotide polymorphism (SNP) in IL‐6 was demonstrated to be involved in glaucoma pathogenesis in patients with NTG." (PMID 34599867, 2021). "We found a nominally significant association of GSTM1 gene deletion with decreased risk of ocular hypertension and a protective role of IL1B rs16944 and IL6 rs1800629 in the risk of glaucoma." (PMID 33803434, 2021). "Several studies have suggested that BAK increases the levels of cytokines such as IL-6, IL-8 and IL-1β in the tears of patients using glaucoma eyedrops and that these inflammatory regulators cause ocular discomfort." (PMID 33271908, 2020). "Together, our data indicate that IL-6 deficiency mitigates glaucoma-induced deficits in visual function and optic nerve structure without improvement in axon transport or reduction in microglia reactivity." (PMID 28620279, 2017). "To ensure detection of any vision loss associated with microbead-induced glaucoma, we performed bilateral injections of microbeads in one cohort of WT and IL-6-/- mice." (PMID 28620279, 2017). "The interleukin-6 (IL-6) family of cytokines and their signal transducer glycoprotein (gp130) are implicated in inflammatory and cell survival functions in glaucoma." (PMID 27747134, 2016). "This contrasts with reports in the retina, which has shown that an IL-6 transducer was elevated under conditions of glaucoma-related stress before RGC loss." (PMID 26376776, 2015). "Altered levels of different miRNAs in AH samples from glaucoma patients may regulate target genes linked to apoptosis and inflammation, such as Bcl-2, caspase-3, IL-6, IL-8, TNF, and nuclear factor κB (NFκB)." (PMID 38333055, 2024). "However, when patients with early to moderate glaucoma were compared to patients with advanced glaucoma, the IL6 rs1800795 C allele as well as the GC genotype were protective against less severe forms of normal-tension glaucoma." (PMID 33803434, 2021). "Other studies have shown that interleukin-6 (IL-6) is linked to the pathogenesis of glaucoma." (PMID 30310698, 2018). "Microglial release of IL-6 in mixed cultures of RGCs, microglia, and astrocytes in response to hydrostatic pressure illustrates an important link between cytokine levels and risk factors for developing glaucoma." (PMID 26376776, 2015). "Higher preoperative levels of TNF-α and IL-6 in aqueous humour may contribute to the development of inflammatory milieu and were associated with worse outcome of glaucoma surgery." (PMID 20467456, 2010). "The MR analysis genetically predicted that the levels of six distinct circulating inflammatory cytokines might be causally linked to the risk of these blinding eye diseases, including MIG for glaucoma, IL-1ra, IL-6, IL-10 and PDGFbb for cataract, and MIG and HGF for macular degeneration." (PMID 38327497, 2024). "Furthermore, IL‐6 has been reported to be associated with the risk and severity of glaucoma." (PMID 34599867, 2021). "For example, the increase in pro-inflammatory factors such as vascular endothelial growth factor (VEGF), interleukin-6 (IL-6), and interleukin-8 (IL-8) accelerates the occurrence and development of glaucoma." (PMID 40486511, 2025).
glaucoma (continued). "IL-6 is one of the key molecules in the inflammatory process and plays a crucial role in various ocular pathologies such as glaucoma, keratoconjunctivitis sicca, as well as corneal neovascularization and fibrosis." (PMID 41343530, 2025). "MCP-1, IL-6, and angiogenin are important immune mediators in predicting primary open-angle glaucoma, participating in related pathological processes, though specific mechanisms require further study." (PMID 40486511, 2025). "The gene polymorphism at the IL-6 (-174) locus is related to some clinical indicators of NTG patients, affecting the expression level or functional activity of IL-6, and thus influencing the occurrence and development of glaucoma." (PMID 40486511, 2025). "It was found that multiple inflammatory factors like Tumor Necrosis factor alpha (TNF – α), Interleukin-6 (IL-6), and Interleukin-1 (IL–1) are abnormal in glaucoma patients’ intraocular fluid." (PMID 40486511, 2025). "On the other hand, IL-6 expression has been previously correlated with neuroprotective, regenerative and proliferative responses in different glaucoma models." (PMID 38337691, 2024). "We found the mRNA expression of cGAS-STING signaling downstream genes Il6, Ifnb, and Cxcl10 were increased in glaucoma as compared to the sham group." (PMID 38848144, 2024). "In a previous study, patients with glaucoma showed higher serum levels of IL-4 and IL-6 and those with severe optic neuropathy showed even higher levels, also suggesting the role of abnormal immune environment in the glaucoma pathogenesis." (PMID 38724620, 2024). "Intense inflammatory staining in the optic nerve head of glaucoma eyes with an elevated proinflammatory BSF-2(IL-6) levels have been witnessed during histological examinations of the human retina." (PMID 38540099, 2024). "According to our meta-analysis findings, resveratrol demonstrates the ability to diminish inflammatory cytokines like iNOS, COX-2, IL-6, and IL-1β in a model of glaucoma-related retinal injury." (PMID 39881870, 2024). "In line with this, the present results show that in the MCE glaucoma model, there was an enhanced expression of both IL-6 and TNF-α, in accordance with previous findings." (PMID 38337691, 2024). "In a glaucoma mouse model, increased expressions of inflammatory cytokines, including interferon-γ, IL-6, IL-4, IL-10, and IL-1β were found." (PMID 37744880, 2023). "Data showed that IL-6 was significantly higher in the tear samples of the glaucoma patients vs. the comparatives (p < 0.0001)." (PMID 37305138, 2023). "In this mouse model of glaucoma in previous work, we found an increase in IL-6 expression at 1, 3 and 5 days after OHT induction in OHT eyes and at 1, 5 and 7 days in contralateral eyes." (PMID 35625676, 2022). "Interleukin-6 (IL-6) has a major role in the pathology of glaucoma, among other systemic inflammatory diseases, and high plasma C-reactive protein (CRP) levels have been associated with normal tension glaucoma." (PMID 35215429, 2022). "IL-6 expression, although not significantly, was increased in ONH of DBA/2J mice; interestingly, we found the IL-6 signal transducer gene (IL-6 st) significantly overexpressed in DBA/2J mice with severe glaucoma." (PMID 34530842, 2021). "An in vitro experimental study showed that IL6 activation regulates fibrosis of the trabecular meshwork induced by TGF-β to attenuate glaucoma progression." (PMID 34823561, 2021). "The current study provides novel insights that pro-inflammatory cytokines such as IL-1β and IL-6 are regulated by δ-opioids via STAT3-dependent pathways in rat glaucoma model." (PMID 33628191, 2021). "Immune inflammatory response mediators like proteolytic enzymes and pro-inflammatory cytokines (TNF-α, IL-1β, IL-6, IL-12, and NO) have recently become a target of glaucoma research." (PMID 33803434, 2021). "In tear samples, an increase in IL-4, IL-12, IL-15, IL-6, and IL-8 in patients with glaucoma have been reported." (PMID 34575451, 2021).